RBMX2 (RNA binding motif protein X-linked 2)
Description:
Involved in pre-mRNA splicing as component of the activated spliceosome. As a component of the minor spliceosome, involved in the splicing of U12-type introns in pre-mRNAs (Probable).
Synonyms: CGI-79; Snu17
Tractability: Small molecule: a structure with a bound ligand is known. PROTAC: UniProt records ubiquitination sites on it; ubiquitination databases record sites on it; its protein half-life has been measured.
Gene: Protein-coding gene on chromosome X (130,401,922 to 130,413,656, forward strand). Ensembl gene ENSG00000134597.
Subcellular location: Nucleus
Subcellular location (Human Protein Atlas): Nuclear membrane; Endoplasmic reticulum; Nucleoli
Pathways (Reactome):
Metabolism of RNA: mRNA Splicing - Major Pathway
Gene Ontology:
Molecular function: protein binding; RNA binding; nucleic acid binding
Biological process: mRNA splicing, via spliceosome; U2-type prespliceosome assembly
Cellular component: nuclear membrane; nucleolus; nucleus; spliceosomal complex; U12-type catalytic step 2 spliceosome; U2-type catalytic step 1 spliceosome; U2-type precatalytic spliceosome; catalytic step 2 spliceosome; nucleoplasm; precatalytic spliceosome; RES complex; U2 snRNP
Homologues: Orthologues: chimpanzee RBMX2 (99% identical), macaque RBMX2 (97% identical), pig RBMX2 (84% identical), dog RBMX2 (81% identical), rabbit RBMX2 (79% identical), guinea pig RBMX2 (78% identical), rat Rbmx2 (77% identical), mouse Rbmx2 (76% identical), zebrafish rbmx2 (55% identical), tropical clawed frog rbmx2 (47% identical), Caenorhabditis elegans rbmx-2 (40% identical), Drosophila melanogaster CG10466 (30% identical). Paralogues in human: CSTF2 (25% identical), CSTF2T (25% identical), ZCRB1 (19% identical), U2AF2 (17% identical), UHMK1 (8% identical).
Diseases named in the same sentence as RBMX2 in open-access papers:
RBMX2 is named in the same sentence as 11 diseases in open-access papers, as found by Europe PMC text mining. Sharing a sentence is not in itself a finding about the gene and the disease. The quoted sentences say what the papers report.
autism (1 paper, 2021). Persistent deficits in social interaction and communication and interaction as well as a markedly restricted repertoire of activity and interest as well as repetitive patterns of behavior. "The RBMX2 gene is also located adjacent to the Solute Carrier Family 25 Member 14 (SLC25A14) gene, which has been shown to have altered expression in autism patients." (PMID 34914762, 2021).
esophageal cancer (1 paper, 2025). A primary or metastatic malignant neoplasm involving the esophagus. "By integrating bioinformatics, experimental validation, and clinical correlation analyses, we identified six SFs (CRNKL1, SNRPB2, RBMX2, DDX46, PPWD1, and CFAP20) that are aberrantly overexpressed in esophageal cancer and tightly linked to poor prognosis." (PMID 40282339, 2025). "Exon 11 skipping of CTTN occurred after knockdown of most survival-related SFs (CRNKL1, SNRPB2, PPWD1, RBMX2, and DDX46), while exon 11 inclusion was observed in esophageal cancer in comparison to normal tissue, both in the TCGA database and in our own full-length sequencing data." (PMID 40282339, 2025).
lung adenocarcinoma (1 paper, 2025). A carcinoma that arises from the lung and is characterized by the presence of malignant glandular epithelial cells. "TIMER2.0 analysis shows elevated RBMX2 expression in lung adenocarcinoma and lung squamous cell carcinoma tissues, validated by immunofluorescence." (PMID 41277807, 2025). "Our findings indicated a notable upregulation of RBMX2 in lung cancer, specifically in lung adenocarcinoma (LUAD) and lung squamous cell carcinoma (LUSC)." (PMID 41277807, 2025). "(F) The expression of RBMX2 and p65 in lung adenocarcinoma (LUAD) and lung squamous cell carcinoma (LUSC) clinical tissues via IF." (PMID 41277807, 2025).
lung carcinoma (1 paper, 2025). "(C) The expression of RBMX2 in different lung cancer cells and normal lung epithelial cells via real-time quantitative polymerase chain reaction (RT-qPCR)." (PMID 41277807, 2025). "The results demonstrated that RBMX2 expression in lung cancer epithelial cell lines (NCIH1299, NCIH460, and CALU1) was significantly higher than that in normal lung epithelial cells (BEAS-2B)." (PMID 41277807, 2025). "To investigate the elevated expression of RBMX2 in lung cancer further, we measured its expression in both lung cancer epithelial cell lines and normal lung epithelial cell lines using RT-qPCR." (PMID 41277807, 2025). "Finally, we silenced RBMX2 in the human lung cancer epithelial cell line H1299, which expresses high levels of RBMX2, to assess the effect on EMT-related proteins, as well as invasion and migration ability following M. bovis infection." (PMID 41277807, 2025). "(D, E) The expression of RBMX2 in lung cancer clinical tissues via IF." (PMID 41277807, 2025). "This study aims to elucidate the molecular mechanisms by which RBMX2 contributes to M. bovis infection and its potential role in infection-associated EMT, thereby providing novel insights into the intersection of TB and lung cancer." (PMID 41277807, 2025). "Additionally, the effective modulation of RBMX2 could potentially mitigate the incidence of TB-associated EMT and its implications for lung cancer development in the near future." (PMID 41277807, 2025). "Notably, the knockout of RBMX2 in this context inhibited EMT, suggesting that RBMX2 may elevate the risk of lung cancer through EMT induction following M. bovis infection." (PMID 41277807, 2025).
neuroblastoma (1 paper, 2020). Neuroblastoma (NB) is the most common solid, extracranial childhood tumor. "For example, in the large SEQC cohort, RBM11, RBM20, RBMX2 were all upregulated in stage 4 neuroblastoma, compared to 4S with RBM47 being downregulated." (PMID 32707690, 2020).
infection (2 papers, 2024 to 2025). The state of being infected such as from the introduction of a foreign agent such as serum, vaccine, antigenic substance or organism. "Real-time quantitative polymerase chain reaction (RT-qPCR) results showed that RBMX2 expression was significantly upregulated after infection with both M. bovis and M. bovis BCG." (PMID 41277807, 2025). "The results indicated that RBMX2 significantly inhibited the EMT process in H1299 cells post-infection." (PMID 41277807, 2025). "(H) Cell adhesion assay was conducted to assess the cell adhesion ratio of RBMX2 knockout EBL cells after infection with M. bovis." (PMID 41277807, 2025). "Plate count assays demonstrated a significant decrease in the adhesion of both M. bovis BCG and M. smegmatis in RBMX2 knockout EBL cells at multiple time points post-infection compared to WT EBL cells." (PMID 41277807, 2025). "We also assessed how varying infection durations influenced RBMX2 knockout EBL cells using GO analysis." (PMID 41277807, 2025). "Collectively, RBMX2 is a novel host factor that enhances M. bovis infection and drives infection-induced EMT." (PMID 41277807, 2025). "Findings showed that RBMX2 knockout EBL cells had a prominent promotion in antioxidant capacity compared with wild-type EBL cells after infection with M. bovis." (PMID 39308873, 2024). "This indicated that M. bovis induced host cells to express more RBMX2 to induce cell death, through which they combat the infection." (PMID 39308873, 2024). "Moreover, the invasion of both mycobacterial species was notably reduced at various hours post-infection in RBMX2 knockout cells." (PMID 41277807, 2025). "To investigate whether RBMX2 mediates intracellular inflammation by regulating the tightness of the epithelial barrier, we measured the mRNA levels of inflammatory factors (IL-1β, TNF, and IL-6) in RBMX2 knockout EBL cells post-infection." (PMID 41277807, 2025). "Based on the high mitochondrial membrane potential in normal cells, the results showed green solid and obscure faint yellow signals in wild-type EBL cells, which uncovered that RBMX2 can promote apoptosis after infection with both virulent M. bovis and avirulent M. bovis BCG." (PMID 39308873, 2024). "In addition, RBMX2, as a global splicing regulatory factor, plays an important role in the host infection of M. bovis." (PMID 39308873, 2024). "Notably, RBMX2 knockout cells exhibited significant resistance to infection." (PMID 41277807, 2025). "To investigate the potential role of RBMX2 in resistance to M. bovis infection, we assessed the survival rate of EBL cells and H1299 cells at different hours post-infection using CCK-8 assay." (PMID 41277807, 2025). "Simultaneously, a CCK-8 assay and Crystal Violet staining uncovered that after M. bovis infection, RBMX2 knockout EBL cells had significantly higher CCK-8 cell proliferation levels than wild-type EBL cells at both 72 and 96 hours post-infection (hpi)." (PMID 39308873, 2024). "Based on the transcriptome sequencing results, we detected the cell apoptosis level and lactate dehydrogenase (LDH) release in RBMX2 knockout EBL cells and wild-type EBL cells after infection with M. bovis." (PMID 39308873, 2024). "Expression of RBMX2 after infection, and RBMX2 did not affect cell proliferation but inhibited cell survival during M. bovis infection." (PMID 41277807, 2025). "Furthermore, the invasion of M. bovis in RBMX2-KO#17 and KO#23 EBL cells was decreased at 2, 4, and 6 hr post-infection compared with WT EBL cells." (PMID 41277807, 2025). "In addition, there was a significant decrease in the release of LDH in RBMX2 knockout EBL cells after infection with M. bovis compared with wild-type EBL cells via an LDH assay, which meant RBMX2 promotes a high level of apoptosis after M. Bovis infection." (PMID 39308873, 2024).
tumor (2 papers, 2025). "RBMX2 is highly expressed in tumor tissues and regulates cancer-related metabolites." (PMID 41277807, 2025). "We explored the relationship between survival-related SFs and ploidy, and found that CRNKL1, SNRPB2, RBMX2, and CFAP20 showed significant positive correlations with tumor ploidy." (PMID 40282339, 2025). "Our analysis of RBMX2 across various cancers revealed increased expression levels in LUAD and LUSC, suggesting a conserved role in tumor biology across species." (PMID 41277807, 2025). "Additionally, immunofluorescence analysis revealed that RBMX2 expression levels were also higher in LUAD and LUSC tumor tissues compared to adjacent non-cancerous lung tissues." (PMID 41277807, 2025).
cancer (1 paper, 2025). A tumor composed of atypical neoplastic, often pleomorphic cells that invade other tissues. "In this context, RNA-binding motif protein X-linked 2 (RBMX2) has emerged as a potential host factor involved in both TB infection and cancer progression." (PMID 41277807, 2025). "Integrated transcriptomic, proteomic, and metabolomic data reveal that RBMX2 regulates epithelial–mesenchymal transition (EMT), a process linked to cancer progression." (PMID 41277807, 2025). "(A) A comparative analysis of the functional domains of the RBMX2 protein across ten different species.(B) Analyzing the expression patterns of RBMX2 in pan-cancer using TIMER2.0 cancer database." (PMID 41277807, 2025). "Despite these insights, the specific function of RBMX2 in the context of M. bovis infection and its potential role in cancer pathogenesis remains largely unexplored." (PMID 41277807, 2025). "To further elucidate the involvement of RBMX2 in cancer, we utilized the TIMER2.0 database to assess its expression patterns across various cancer types within The Cancer Genome Atlas (TCGA)." (PMID 41277807, 2025).
RBMX2 also shares sentences with these, for which no sentence is quoted: bipolar disorder (1 paper); lung squamous cell carcinoma (1); microcephaly (1).